ZFP2 (ZFP2 zinc finger protein)
Description:
Probable transcription factor involved in neuronal differentiation and/or phenotypic maintenance.
Synonyms: Zfp-2; ZNF751; FLJ21628
Tractability: PROTAC: ubiquitination databases record sites on it.
Gene: Protein-coding gene on chromosome 5 (178,895,889 to 178,933,415, forward strand). Ensembl gene ENSG00000198939.
Subcellular location: Nucleus
Pathways (Reactome):
Gene expression (Transcription): Generic Transcription Pathway
Gene Ontology:
Molecular function: protein binding; DNA-binding transcription factor activity, RNA polymerase II-specific; RNA polymerase II cis-regulatory region sequence-specific DNA binding; sequence-specific double-stranded DNA binding
Biological process: regulation of transcription by RNA polymerase II
Cellular component: nucleus
Genetic constraint (gnomAD): Loss-of-function variants: 36 observed, 40.03 expected, observed/expected ratio (o/e) 0.9, 90% interval 0.69 to 1.19. The upper end of that interval is the gene's LOEUF score, 1.19, which puts it in group 5 of 6, group 1 being the genes least tolerant of losing a copy. Missense variants: 522 observed, 581.09 expected, observed/expected ratio (o/e) 0.9, 90% interval 0.83 to 0.97. Synonymous variants: 170 observed, 189.57 expected, observed/expected ratio (o/e) 0.9, 90% interval 0.79 to 1.02.
Homologues: Orthologues: chimpanzee ZFP2 (99% identical), macaque ZFP2 (97% identical), dog ZFP2 (91% identical), guinea pig ZFP2 (88% identical), rat Zfp2 (86% identical), mouse Zfp2 (85% identical), rabbit ZFP2 (83% identical), pig ZFP2 (80% identical). Paralogues in human: ZNF879 (54% identical), ZNF33B (52% identical), ZNF568 (52% identical), ZNF471 (52% identical), ZNF7 (52% identical), ZNF708 (51% identical), ZNF658 (51% identical), ZNF182 (51% identical), ZFP28 (51% identical), ZFP3 (51% identical), ZNF16 (51% identical), ZNF189 (51% identical), and 164 more.
Diseases named in the same sentence as ZFP2 in open-access papers:
ZFP2 is named in the same sentence as 5 diseases in open-access papers, as found by Europe PMC text mining. Sharing a sentence is not in itself a finding about the gene and the disease. The quoted sentences say what the papers report.
liver cancer (1 paper, 2026). An epithelial or non-epithelial malignant neoplasm that arises from the liver. "In an oleic acid (OA)-induced lipid overload model using human liver cancer cells (HepG2), ZFP2 significantly reduced intracellular lipid accumulation and improved lipid profiles." (PMID 41623966, 2026).
meningitis (1 paper, 2025). A disorder characterized by acute inflammation of the meninges of the brain and/or spinal cord. "As infections primarily occur via inhalation and progress to fatal meningitis via blood–brain barrier penetration, targeting Zfp2’s regulatory pathways could disrupt virulence while sparing commensal fungi." (PMID 41440694, 2025).
cancer (1 paper, 2025). A tumor composed of atypical neoplastic, often pleomorphic cells that invade other tissues. "ZFP2 and ZNF264 are zinc finger proteins regulating gene expression; their dysfunctions can cause developmental abnormalities and cancer." (PMID 40141456, 2025).
cardiovascular disease (1 paper, 2020). "Variants in ZFP2 are associated with MI in African Americans, though ZFP2 rs953741 has not been previously associated with cardiovascular disease related outcomes." (PMID 33171725, 2020).
ZFP2 also shares sentences with these, for which no sentence is quoted: infection (1 paper).